TNF (tumor necrosis factor)
Diseases named in the same sentence as TNF in open-access papers (continued):
Sharing a sentence is not in itself a finding about the gene and the disease.
uveitis (continued). "At anti-TNF-a start patients in the ORI group presented significantly longer duration of cDMARDs treatment, greater rate of uveitis history, higher JADAS scores and uveitis activity." (PMID 37848930, 2023). "Looking at the TNF-α and VEGF mRNA expressions in the eye tissues of the uveitis group, a statistically significant increase was observed compared with the healthy group (P<0.001)." (PMID 37051104, 2023). "Uveitis in VKHD patients showed the dominant role of clonally expanded Th1‐like effector CD4+ T cells expressing IFNG and TNF." (PMID 37720629, 2023). "Uveitis control was the indication for DMARD therapy in two subjects; combined DMARD and anti-TNF therapy was used in two subjects for uveitis control." (PMID 36038721, 2023). "To evaluate the pathogenesis of uveitis, we measured the protein levels of Ang1, Ang2, VEGFA, TNF-α, IFN-γ, and IL-17 in vitreous humor samples of uveitis patients." (PMID 38015876, 2023). "In the whole cohort, uveitis had been resistant to previous topical and systemic steroids, MTX, and other synthetic and biological DMARDs, including ≥1 TNF-α inhibitor." (PMID 36979992, 2023). "Systemic treatment of uveitis with neutralizing antibodies against rodent TNF-α ameliorated pathologies observed in the EAU model, further validating an important role for TNF-α in uveitis." (PMID 35579886, 2022). "Lutein treatment reduced the levels of nitric oxide (NO), tumor necrosis factor (TNF)-α, interleukin (IL)-6 prostaglandin (PGE-2) and monocyte chemotactic protein (MCP-1) in the aqueous humor of mice with endotoxin-induced uveitis." (PMID 35885268, 2022). "Off-label use of other systemic TNFα antagonists has also been reported, and expert panel recommendations published in 201417 suggest that infliximab and adalimumab could be used to treat a number of inflammatory ocular conditions, including several forms of uveitis." (PMID 35704329, 2022). "Adalimumab, an anti-tumor necrosis factor alpha (TNFα) monoclonal antibody, is the only licensed biologic therapy for JIA-uveitis." (PMID 34627340, 2021). "The search terms included uveitis, iridocyclitis, retinitis, retinal vasculitis, panuveitis, uveit*, adalimumab, ADA, Humira, TNF, TNF-a, anti-tumor necrosis factor-alpha, randomized controlled trial, and clinical trial." (PMID 33981245, 2021). "Additionally, biologic DMARD therapies—although costly—may be cost-effective in childhood rheumatologic disease: tumor necrosis factor (TNF) inhibitors for the treatment of JIA and JIA-associated uveitis, for example, are potentially cost-effective from a health payer perspective." (PMID 34488779, 2021). "In such patients, if no proper, frequent ophthalmologic assessment is possible, an anti-TNF antibody treatment, such as adalimumab, or the CTLA-4Ig abatacept may be privileged, as these biologics are most likely to prevent, to a large extent, the risk of developing uveitis." (PMID 34208973, 2021). "Lutein treatment reduced the concentrations of nitric oxide (NO), tumor necrosis factor (TNF)-α, interleukin (IL)-6, prostaglandin (PG)E2, and monocyte chemoattractant protein (MCP)-1 in aqueous humor of mice with endotoxin-induced uveitis." (PMID 34573081, 2021). "The keywords ophthalmic complication, uveitis, inflammatory eye disease, optic neuritis, neuropathy, adverse events, anti-TNF, TNF alpha inhibitor, infliximab, etanercept, adalimumab, golimumab, certolizumab, and biologics were used for this search." (PMID 32337619, 2020). "In the case of etanercept, uveitis, IBD flares, and granulomatous diseases have been shown to be more prevalent compared to other TNF blockers." (PMID 32508634, 2020). "Adalimumab (a fully humanized monoclonal antibody that blocks the interaction between TNF-α and TNF R1 and TNF R2 receptor) and infliximab (a chimeric monoclonal antibody directed against TNF-α) were mostly studied in uveitis treatment." (PMID 33171664, 2020).
uveitis (continued). "Etanercept (Enbrel®, Immunex Corporation, Seattle, WA, USA) is a fusion protein that blocks TNF-α and TNF-β and has been found to be ineffective for uveitis treatment." (PMID 31448093, 2019). "A previous study also showed reduced rates of uveitis and IBD flares in patients treated with anti-TNF agents." (PMID 29420599, 2018). "As a significant proportion of children with moderate-severe uveitis are refractory to MTX, biologics in the form of monoclonal anti-TNF agents have been tried." (PMID 30886955, 2018). "Examination of blood and ocular fluid samples from affected persons with uveitis indicates high levels of TNF-α, and TNF-α blockade is often highly effective in patients with recalcitrant inflammation." (PMID 27293321, 2016). "Ma and Bai found that Z-ligustilide significantly inhibited NF-κB activation and the production of IL-1β and TNF-α in experimental ovariectomized (OVX) osteopenic rats and endotoxin-induced uveitis rats." (PMID 27872860, 2016). "Polymers imbedded with non-steroidal immunosuppressive drugs, such as cyclosporine A and anti-TNF are in development and could provide an excellent alternative to the current sustained release corticosteroid delivery devices available for the treatment of uveitis and other ocular disease." (PMID 26264035, 2015). "Recently, anti-TNF agents, including infliximab and adalimumab, have shown to be very effective in JIA patients who present with refractory uveitis." (PMID 24886032, 2014). "We observed that BD patients with active uveitis showed significantly higher levels of IFN-γ and TNF-α compared to healthy subjects." (PMID 24994946, 2014). "In summary, we used silibinin to inhibit TNF-α- or IFN-γ-mediated mature ICAM-1 expression in ARPE-19 cells in vitro, which is a key event in the pathogenesis of uveitis." (PMID 25032222, 2014). "While anti-TNF agents have a significant impact on the management of JIA, experience on their effects on uveitis remains limited, particularly in younger patients." (PMID 24886032, 2014). "TNF-α appears to play a role in the pathogenesis of uveitis and therefore TNF-α blockade is a rational therapy for uveitis refractory to standard treatment." (PMID 24489444, 2013). "Elevated levels of intraocular IL-6 and TNF-α, whose expression is upregulated by IRF5, have been reported in patients with intermediate uveitis, especially in those with macular edema." (PMID 24116155, 2013). "The ocular fluids from BD patients with active uveitis contained significant amounts of inflammatory cytokines, such as IFN-γ, IL-2, TNF-α, IL-6, and IL-17." (PMID 22546542, 2012). "Anti-TNF agents like etanercept (ETN), adalimumab, and INF have been successfully used in the management of treatment refractory uveitis and several retrospective case series describe the use of INF in pediatric uveitis." (PMID 22389806, 2012). "Ocular fluids from active uveitis patients who have BD contained significant amounts of inflammatory cytokines such as IFN-γ, IL-2, TNF-α, IL-6, and IL-17, while ocular fluids from infliximab patients did not contain any inflammatory cytokines." (PMID 22546542, 2012). "Recent studies have revealed many similarities between TNF-α blockers and IFN-α therapies for uveitis." (PMID 22454752, 2011). "The introduction of biologic agents such as tumor necrosis factor-alpha (TNF-α)antibodies and interferon alpha (IFN-α) provides a new intervention regimen forpatients with refractory uveitis." (PMID 21611186, 2011). "Assessment of cytokines in uveitis patients revealed the presence of Interleukin (IL)-2, 6, 10, 12, Interferon (IFN)-γ, tumor growth factor (TGF)-β2, tumor necrosis factor (TNF)-α, and macrophage migration inhibitory factor." (PMID 19145248, 2009). "In contrast with the rise of adalimumab, the downward trajectory of etanercept underscores that not all TNF-α inhibitors are equally effective for uveitis." (PMID 41286205, 2025).
uveitis (continued). "These patients developed uveitis between one and twelve years before HS was diagnosed, notably, none of them were on anti-TNF-α therapy." (PMID 41142785, 2025). "Current treatment approach (steroid eye drops, followed by methotrexate, followed by TNF alpha inhibitor) for non-infectious paediatric uveitis results in good VA outcome for most patients." (PMID 40341441, 2025). "In our current study, we performed ELISA to assess the protein levels of IL-10, IL-6, IL-17A, and TNF-α in the serum of non-infectious uveitis patients." (PMID 40433375, 2025). "Adalimumab, a fully humanized IgG1 monoclonal antibody with high affinity for TNF-α, has demonstrated robust efficacy and safety in treating noninfectious uveitis and is widely used in clinical practice." (PMID 41303213, 2025). "The anti-inflammatory properties of fucoxanthin were assessed in a study on endotoxin-induced uveitis (EIU) in rats, where it was demonstrated to lower levels of nitric oxide, prostaglandin-E2 and tumor necrosis factor (TNF)-α in the aqueous humor in a similar way to prednisolone." (PMID 38667772, 2024). "The APTITUDE trial assessed tocilizumab’s effectiveness in patients with uveitis associated with JIA, particularly in those who did not respond to combined treatment with anti-TNF-α and MTX." (PMID 39062219, 2024). "Two commonly used anti-TNF mAbs for the treatment of noninfectious uveitis are adalimumab (ADA) and IFX." (PMID 39449328, 2024). "Thus, it is the only anti-TNF-alpha inhibitor approved by the Food and Drug Administration (FDA) for use in uveitis." (PMID 39254907, 2024). "Contrary to adalimumab, infliximab is an intravenously administered, chimeric human-mouse monoclonal IgG1 targeting TNFα and is not licensed in the UK for the treatment of uveitis." (PMID 37848676, 2024). "This review aims to explore the use of biologic agents like TNF alpha inhibitors and other agents and intravitreal drug delivery in the treatment of non-infectious uveitis." (PMID 39157460, 2024). "Adalimumab is the only TNF-α inhibitor which has gained approval for management of non-infectious uveitis." (PMID 39157460, 2024). "Electronic Medical Record (EMR) chart review of 394 non-infectious uveitis patients on anti-TNF therapy focused on identifying patients seen by uveitis specialists at a single institution who were on anti-TNF therapy and had developed neurological symptoms." (PMID 39078559, 2024). "Infliximab, certolizumab, golimumab, and etanercept are among several other TNF-α inhibitors that do not have FDA approval for the treatment of non-infectious uveitis." (PMID 39157460, 2024). "For severe uveitis in JIA, a combination of MTX and anti-TNF-α biologic treatment is advised." (PMID 39062219, 2024). "Presenting visual acuity, duration of the disease before starting anti-TNF-α therapy, type of anti-TNF-α drug, anatomical type of uveitis and etiological type of uveitis were the variables included in univariate analysis of predictors of moderate to severe visual loss." (PMID 36831165, 2023). "The levels of Ang2, VEGFA, and TNF-α were not significantly different between the uveitis group and the control group (P = 0.16–0.91)." (PMID 38015876, 2023). "Serious side effects with long-term anti-TNF α use in non-infectious pediatric uveitis remains rare, infliximab antibodies is the most frequent issue." (PMID 37990307, 2023). "Even if there is no comparative phase III study, several clinical experiences support its use in patients with uveitis who did not respond to anti-TNF drugs." (PMID 37700264, 2023). "Regarding biologic therapy, adalimumab was the first anti-TNF approved by the FDA for the management of non-infectious uveitis in 2016." (PMID 37386509, 2023). "More recent biotherapies such as anti-TNF are also very effective (as they are in other non-infectious uveitis etiologies)." (PMID 37176633, 2023).
uveitis (continued). "Indeed, MIA-602, but not GHRH agonist MR-409, reduced the infiltration of macrophages and leucocytes and the production of TNF-α, IL-1β and MCP-1 in a preclinical model of LPS-induced uveitis." (PMID 37649486, 2023). "Several cellular junction proteins maintain the BRB, and during bacterial infection and other ocular inflammation models (e.g., uveitis and glaucoma), increased inflammatory mediators (e.g., IL-6, MIP2, TNF-α, and IL-1β) can impair the barrier properties (24, 62, –, 66)." (PMID 35913202, 2022). "Several studies have evaluated the curative effect of TNF-α inhibitors, including infliximab and adalimumab, in patients with ocular inflammation, including uveitis and scleritis, without subgroup analysis." (PMID 36431163, 2022). "Our outcome is concordant with previous uveitis investigations in which the tear profile was analysed, emphasising that tear TNF-α levels do not reflect the concentrations within the eye." (PMID 36498608, 2022). "Adalimumab, an inhibitor of tumor necrosis factor-alpha, is a systemic non-corticosteroid agent approved for the treatment of noninfectious uveitis." (PMID 36451402, 2022). "Early use of anti-TNF is recommended if uveitis is not or is partially responsive to the initial treatment associating systemic corticosteroids and a conventional DMARD to prevent visual loss especially if patient is in a sight-threatening situation." (PMID 35979409, 2022). "The levels of EGF, fractalkine, IL1-β, IL-17A, IL-1RA, IL-2, IL-23, IL-8, IP-10, TNF-α and IL-6 in patients with uveitis in their active phase were independent of their counterpart levels in plasma, the difference being statistically significant (p < 0.05)." (PMID 36498608, 2022). "Therefore, the objective of this review is to provide a background on the role of TNF-α in the immunopathogenesis of uveitis, as well as from bench to clinical research progress, to better guide TNF-α-based therapeutics for uveitis." (PMID 34795583, 2021). "In this regard, significantly lower levels of TNF-α, IL-6, MIP-1α and leukocytes, as well as histological evaluation of TAC-HPβCD compared to EIU group confirms the effectiveness of this formulation in the treatment of uveitis." (PMID 34684030, 2021). "The expression levels of TNF-α and IFN-γ are positively correlated with the severity of uveitis." (PMID 34778467, 2021). "Her renal function was stabilized with cyclophosphamide pulse therapy followed by corticosteroids and multiple immunosuppressants, while her meningitis, uveitis, and CRP levels significantly improved with IL-1-receptor antagonist anakinra, other than TNF-α monoclonal antibody therapy." (PMID 34249981, 2021). "In this sense, significantly higher levels of TNF-α, IL-6, IL-8, MIP-1α and leukocytes, as well as histological evaluation of EIU group, compared to healthy group confirmed the correct development of the uveitis model." (PMID 34684030, 2021). "In addition, some studies have shown that levels of inflammatory cytokines elevated in adults with RA, such as IL-6 and TNFα, are also elevated in the synovial fluid and serum of patients with JIA, as well as the aqueous humor of patients with JIA-uveitis." (PMID 34627340, 2021). "In the same year, clinical trials were performed on the effectiveness of CZP for refractory spondyloarthritis-related uveitis, but no significant advantages were found over other anti-TNF-α agents." (PMID 34795583, 2021). "In RCTs assessing anti-TNF and anti-IL17A in axSpA, incident uveitis are rare events." (PMID 34271991, 2021). "TNF-α inhibitors, which can bind to and deactivate TNF-α, indicate the pathogenesis of uveitis." (PMID 35096888, 2021). "ADA was the first anti-TNF-α antibody indicated for non-infectious uveitis by the FDA, the European Medicines Agency and the National Medical Products Administration (NMPA) of China." (PMID 35096888, 2021).
uveitis (continued). "This is not likely coincident, because the use of TNF inhibitors was rapidly increased after official approval of infliximab and adalimumab for the BD related uveitis at 2007 and 2016, respectively, in Japan." (PMID 33522943, 2021). "Increased concentrations of TNF-α in tissue drive T cell responses and macrophage activation in non-infectious uveitis." (PMID 34054864, 2021). "TNF-α is upregulated in different retinopathies, such as proliferative DR26 and uveitis." (PMID 34520511, 2021). "Most importantly, the essential role of TNF in uveitis has been confirmed by the recent success of employing the TNF-inhibitor adalimumab in the treatment of non-infectious uveitis." (PMID 32458144, 2020). "Through large controlled studies indicating decrease in the number of uveitis flares, the role of TNF inhibitors therapy for non-infectious uveitis gained more ground." (PMID 32337619, 2020). "The most newly published guidelines for uveitis management suggest a step-ladder approach, starting with topical, periocular, and systemic CS, followed by IMT, and finally the use of biologic therapy (preferably a TNF-α inhibitor)." (PMID 32508634, 2020). "A recent study has indicated that both golimumab and certolizumab represent effective and safe options for patients with uveitis even if the result with other anti-TNF-α drugs has not been successful." (PMID 32508634, 2020). "More recently, “biologic” therapies targeting TNFα have been used, based on the apparent involvement of TNFα in the pathogenesis of EAU, as well as evidence that TNFα levels are increased in aqueous humor of patients with uveitis." (PMID 33569048, 2020). "While the inflammatory cytokine, TNF-α, was not statistically significant, it was undetectable in healthy controls, but was 1.9 ± 0.7 ng/mL (mean ± SD) in PBMCs from 13 uveitis patients." (PMID 31729418, 2019). "Despite the high occurrence of uveitis in the present study population, none of the previously reported TNF-α SNPs -308G/A, -238G/A, -857C/T were found in this cohort." (PMID 30779760, 2019). "Despite these benefits, most studies show that approximately 50% of patients with non-infectious uveitis treated with anti-TNF are unresponsive/intolerant." (PMID 31523783, 2019). "Anti-TNF biologics are a class of medications that target TNF directly as monoclonal antibodies or the TNF receptor to block the cytokine cascade and successfully modify disease activity in a milieu of rheumatic diseases (e.g., RA, JIA, uveitis)." (PMID 30774631, 2019). "Adalimumab (ADA), a recombinant human immunoglobulin (IgG1) monoclonal antibody that specifically binds to TNF-α, is the only systemic noncorticosteroid agent currently approved for the treatment of noninfectious primary or secondary uveitis." (PMID 30881221, 2019). "Furthermore, MMP-2, as an activating sheddase of TNF-α, facilitates the secretion of active TNF-α, contributing to the chronicity of uveitis." (PMID 29686615, 2018). "Interestingly, a high expression of ICOS on CD4+ T cells has been described in BD patients with active uveitis, suggesting a role in the pathogenesis of uveitis, possibly through upregulation of IFN-g, IL-17, and TNF." (PMID 29850627, 2018). "Unfortunately, anti-tumour necrosis factor (anti-TNF) therapy is not the panacea either for JIA alone, or JIA-associated uveitis." (PMID 30886955, 2018). "We focused on these drugs although other agents that are often used in the treatment of clinical uveitis such as alkylating agents (cyclophosphamide etc.), antimetabolites (azathioprine, MTX) and anti-TNF antibody, may also have an effect on IRF8 methylation." (PMID 28432342, 2017). "Other biologic agents targeting immune cells can be utilized with pediatric uveitis patients who do not respond to anti-TNF therapy." (PMID 27800265, 2016).